ERF (ETS2 repressor factor)
Diseases named in the same sentence as ERF in open-access papers (continued):
Sharing a sentence is not in itself a finding about the gene and the disease.
cancer (12 papers, 2006 to 2025). A tumor composed of atypical neoplastic, often pleomorphic cells that invade other tissues. "We found an increased abundance of the transcription factors AHDC1 and ERF, as well as proteins associated with cancer stemness (AQP5 and ASB6), which were higher expressed in SBT-MP when compared to SBT." (PMID 38014221, 2023). "Additional members of the pedigree who had been previously sampled were assayed for the ERF variant (ThermoFisher (Waltham, MA, USA) assay: C__25967527_10) to test for segregation of the variant with cancer." (PMID 34063511, 2021). "One example corresponds to a copy of the gene encoding the ETS-2 repressor factor (ERF), a gene that regulates proliferation of some types of cancer cell lines." (PMID 16846249, 2006). "Furthermore, for many of these TFs, such as TFEC, IRF5, and ERF, we found a significant association between TF expression and cancer prognosis using TCGA data, suggesting that the dysregulation of these TFs can also impact cancer outcomes." (PMID 39013578, 2024). "Pedigree studies based on the UPDB have previously provided the identification of BRCA1 and BRCA2, and more recently have identified additional rare cancer predisposition variants (GOLM1; CELF4; FANCM; ERF; LRBA; FGF5) in similar sets of sampled high-risk pedigrees." (PMID 38136396, 2023). "Overall, these results suggested that SP1 activated ABCC1 and stimulated the expression of the CCNE1, ERF, and MYB genes, which have been shown to be related to chemoresistance and cancer relapse." (PMID 31118037, 2019). "We did not seek detailed cancer family histories in our cohort and have not undertaken extended testing to identify ERF carriers in the wider family of our cohorts and so we cannot address whether there is an increased cancer risk in these families." (PMID 30758909, 2019).
bacterial infection (3 papers, 2013 to 2026). "For example, an Arabidopsis ERF/AP2 transcriptional repressor, AtERF4, is transcriptionally up-regulated by bacterial disease but negatively regulates disease resistance." (PMID 24043853, 2013).
neurodevelopmental disorder (1 paper, 2023). A behavioral and cognitive disorder with onset during the developmental period that involves impaired or aberrant development of intellectual, motor, or social functions. "Four of the 18 high confidence variants (in ERF, SETD1A, SHANK3 and ZBTB18) were recurrent, with these variants having been reported previously in individuals with neurodevelopmental disorders." (PMID 36117209, 2023). "Only two probands (11%) with genetic diagnoses (SETD1B (ID10), ERF (ID18)) had CAS without co-occurring neurodevelopmental disorder diagnoses." (PMID 36117209, 2023).
ERF also shares sentences with these, for which no sentence is quoted: Chiari malformation (2 papers); craniosynostosis 4 (2); acanthosis nigricans (1); Alagille syndrome (1); Ataxia (1); chronic heart failure (1); colorectal adenocarcinoma (1); colorectal cancer (1); craniosynostosis 6 (1); craniosynostosis syndrome (1); diabetes mellitus (1); Diamond-Blackfan anemia (1); familial prostate cancer (1); glioma (1); immune dysfunction (1); Intellectual disability (1); intracranial hypertension (1); iron (1); Jackson-Weiss syndrome (1); mild cognitive impairment (1); Muenke syndrome (1); osteoporosis (1); Pleuritis (1); prostate (1); psoriasis (1); psychiatric disorder (1); Saethre-Chotzen syndrome (1); Sepsis (1); Sotos syndrome (1); speech disorder (1).
A further 3 diseases each share a sentence with ERF in 1 paper.